FFAR4 (free fatty acid receptor 4)
Diseases named in the same sentence as FFAR4 in open-access papers (continued):
Sharing a sentence is not in itself a finding about the gene and the disease.
Insulin resistance (40 papers, 2013 to 2025). Increased resistance towards insulin, that is, diminished effectiveness of insulin in reducing blood glucose levels. "FFAR4 variants, particularly rs17108973, can modulate the effect of n-3 FAs on insulin-related traits, particularly insulin resistance, after a six-week supplementation with high doses of n-3 FAs." (PMID 29113108, 2017). "We hypothesized that increased FFAR2 expression and reductions in FFAR4 and SCD1 expression in SAT of type 2 diabetes mellitus patients associate positively with insulin resistance and impaired beta cell function." (PMID 30190473, 2018). "Here, we hypothesized that increased FFAR2 expression and reduced FFAR4 and SCD1 expression in SAT of patients with type 2 diabetes mellitus in the fasted state associate positively with insulin resistance and inversely with beta cell function." (PMID 30190473, 2018). "Using a stepwise bidirectional regression model adjusted for the effects of age, sex and body mass index (BMI), the contribution of FFAR4 SNPs to the variance of baseline index values of homeostatic model assessment of insulin resistance (HOMA-IR) or insulin levels was estimated." (PMID 29113108, 2017). "On the other hand, activation of Ffar4 with synthetic ligands including compound A, TUG-891, or compound 34 generally improves metabolic dysfunction and insulin resistance." (PMID 37075982, 2023). "Activation of FFAR4 can enhance GLP-1 secretion and improve insulin resistance and chronic inflammation in obese mice, and improve colonic permeability in inflammatory bowel diseases mice." (PMID 35516426, 2022). "Only a few studies exist on GPR119, free fatty acid receptor 1 (FFAR1/GPR40) and 4 (FFAR4/GPR120), and the bile acid receptor GPBAR1 (TGR5) as a developer of insulin resistance and β-cell dysfunction, receiving particular attention as targets for therapeutic interventions in diabetic patients." (PMID 35885041, 2022).
diabetes (26 papers, 2014 to 2026). "4-CMTB and GSK137647 were nominated to this study; nevertheless, still, few other FFAR agonists are available, like TUG841, an FFAR4 agonist which is widely investigated in numerous conditions, including diabetes, atherosclerosis, and lung cancer." (PMID 39432182, 2024). "Clinical trials targeting FFAR4 are abundant in the treatment of diabetes-related metabolic disorders, highlighting the potential diverse utility of this receptor in the treatment of lipid- and inflammatory-related diseases." (PMID 37108233, 2023). "FFAR4 has been identified as a new target for diabetes treatment, and it is essential to investigate how FFAR4 affects glucose homeostasis." (PMID 37787527, 2023). "Among them, the free fatty acid receptor (FFAR) FFAR1 (GPR40), FFAR2 (GPR43), FFAR3 (GPR41), and FFAR4 (GPR120) may bridge the genetic and environmental aspects of diabetes (14, –, 18)." (PMID 37787527, 2023). "Selective activation of GPR120 or free fatty acid receptor 4 (FFAR4) has therapeutic potential for the treatment of many diseases, including type 2 diabetes mellitus, osteoporosis, inflammation, and obesity." (PMID 41419665, 2026). "Whereas M3 receptors are expressed in a wide variety of tissues, precluding their selection as drug targets for diabetes, FFAR1 (GPR40) and FFAR4 (GPR120) are Gαq-coupled long-chain fatty acid receptors that have been a focus for small molecule development." (PMID 26661410, 2016). "To this end, we analyzed FFAR2 as well as FFAR4 and SCD1 mRNA and protein expression in SAT of 25 metabolically well-characterized patients with newly diagnosed type 2 diabetes mellitus and 25 age-matched, sex-matched, and BMI-matched glucose-tolerant humans (CON)." (PMID 30190473, 2018). "Free Fatty Acid receptor 4 (FFA4), also known as GPR120, is a G-protein-coupled receptor (GPCR) responsive to long-chain fatty acids that is attracting considerable attention as a potential novel therapeutic target for the treatment of type 2 diabetes mellitus (T2DM)." (PMID 28734639, 2017).
type 2 diabetes (23 papers, 2014 to 2026). "Furthermore, we hypothesized that increased FFAR2 and reduced FFAR4 expression in AT of type 2 diabetes patients associate with parameters of dyslipidemia." (PMID 30190473, 2018). "Long‐chain fatty acid/FFAR4 signaling, which is responsible for incretin secretion, is an attractive pharmaceutical target for the treatment of type 2 diabetes." (PMID 34535977, 2021).
breast carcinoma (12 papers, 2017 to 2024). "In conclusion, we have confirmed the aberrant expression of FFAR4 in human breast cancer patients and demonstrated that FFAR4 can risk-stratify tamoxifen-treated HRPBC patients." (PMID 30795784, 2019). "In some tumors, FFAR1 and FFAR4 have similar effects, and the activation of FFAR1 and FFAR4 can promote the proliferation and migration of breast cancer cells and enhance the growth of colon cancer cells." (PMID 35785152, 2022). "With FFAR4 and its endogenous ligands in breast cancer tissues identified, we next examined its prognostic value in patients." (PMID 30795784, 2019). "We also found elevated proportions or quantities of other long-chain fatty acids in breast cancer tissues with previously unconfirmed FFAR4 affinity (e.g. C20:4n-6, arachidonic acid, AA)." (PMID 30795784, 2019). "FFAR4 expression was assessed by immunohistochemistry in an exploration cohort of 307 breast cancer cases collected from two independent institutes." (PMID 30795784, 2019). "In this report, we showed that FFAR4 is aberrantly expressed in human breast cancer, and identified several endogenous FFAR4 ligands with elevated proportions in breast cancer tissues." (PMID 30795784, 2019). "Interestingly, in HRPBC patients, FFAR4 expression was associated with higher Ki-67 index (P = 0.008) and to a lesser extent, worse histological grade (P = 0.087), suggesting that higher FFAR4 expression in HRPBC patients might be associated with more aggressive breast cancer phenotypes in HRPBC." (PMID 30795784, 2019). "In the exploration cohort, FFAR4 was demonstrated as an independent prognostic factor for recurrences (HR: 2.183, 95% CI: 1.360–3.504, P = 0.001) and breast cancer-specific deaths (HR: 2.102, 95% CI: 1.173–3.766, P = 0.013) in HRPBC cases." (PMID 30795784, 2019). "A synthetic FFAR4 antagonist is already available for research purposes, and it is essential to perform further investigations to provide breast cancer patients with potential treatment options, especially in tamoxifen resistant HRPBC cases." (PMID 30795784, 2019). "FFAR4 signalling has antitumour effects in prostate and colorectal adenocarcinomas, while it has been reported to be a procarcinogenic receptor in the development of breast cancer." (PMID 38243188, 2024). "FFAR4 could be a novel potential target for anti-breast cancer therapy, especially for patients with endocrine resistance." (PMID 38497715, 2024). "Aberrant FFAR4 expression was detected in the breast cancer tissues while normal breast epithelial cells remained negative, indicating FFAR4 may play a role in breast cancer biology." (PMID 30795784, 2019). "The evidence indicated that FFAR4 might be involved in breast cancer biology, but whether FFAR4 affects breast cancer in clinical settings remains enigmatic." (PMID 30795784, 2019). "During previous experiments, we found that FFAR4 was also expressed in human breast cancer tissues." (PMID 30795784, 2019). "FFAR4 may serve as a potential target for anti-breast cancer therapies, especially in endocrine resistant cases." (PMID 30795784, 2019). "We first analyzed FFAR4 expression by IHC in 307 breast cancer cases in the exploration cohort." (PMID 30795784, 2019). "The distinguishing results from different breast cancer subtypes reveals that the prognostic value of FFAR4 might only apply to HRPBC patients (Luminal A, Luminal B HER2 negative and Luminal B HER2 positive)." (PMID 30795784, 2019). "In the case of FFAR4, it is known that FFAR4 is also expressed in adipocytes and macrophages, both cell types are abundantly present in breast cancer tissues and may affect FFAR4’s expression read-out in microarray datasets." (PMID 30795784, 2019). "Our results suggest a novel role of FFAR4 in breast cancer endocrine resistance and it may serve as a potential target for future therapeutic strategies." (PMID 30795784, 2019).
breast carcinoma (continued). "Based on the accumulating evidence of FFAR4 and its ligands in breast tissues, we hypothesized that breast cancer cells may utilize fatty acids in situ as stimulating signals via expressing FFAR4 and therefore exert detrimental effects on disease outcome." (PMID 30795784, 2019). "Finally, an oncogenic role for FFAR4 has also been observed in breast cancer, where it promotes migration and epithelial to mesenchymal transition in cells and metastasis in a xenograft model, and in pancreatic cancer cells, where FFAR4 stimulates cellular motility." (PMID 33113952, 2020). "The altered fatty acid profiles indicated that despite fatty acid expenditure, certain long-chain fatty acids were preserved, or de novo synthesized during breast tumorigenesis and progression, and thus may serve as ligands for FFAR4 and affect breast cancer biology and patient outcome." (PMID 30795784, 2019). "ω-3 PUFA exerted effects can be classified as FFAR4-dependent and FFAR4-independent, the ω-3 PUFA’s suppressive effects on breast cancer is FFAR4-independent, as Chung and colleagues demonstrated using a FFAR4-knockout model." (PMID 30795784, 2019). "With FFAR4/ligand presence in breast cancer tissues confirmed, we next compared RFS and BCSS between FFAR4-high and FFAR4-low patients in the exploration cohort (n = 307) collected from 2 independent institutions." (PMID 30795784, 2019). "Altogether, our results demonstrate FFAR4 as a prognostic biomarker in HRPBC patients and as a potential target for breast cancer therapies, especially in endocrine resistant cases." (PMID 30795784, 2019). "FFAR4 exhibited membranous and cytoplasmic localization and was differentially expressed in breast cancer cells while remaining negative in normal breast epithelial cells." (PMID 30795784, 2019). "On the other hand, pathologists can easily rule out FFAR4 staining on cell types other than breast cancer cells in IHC-stained sections." (PMID 30795784, 2019). "Second, given FFAR4’s negative impact on breast cancer prognosis, FFAR4 signaling pathway may provide novel targets for future anti-breast cancer therapies." (PMID 30795784, 2019). "Besides FFAR4 expression, FFAR4 ligand distribution in situ is also of great concern, as previous investigations on fatty acid composition in human breast tissues didn’t include breast cancer tissues, and none of these studies were conducted in Chinese cohorts." (PMID 30795784, 2019).
colitis (11 papers, 2017 to 2025). Inflammation of the colon. "To characterize the mechanism of anti-inflammatory action of FFAR4 agonist GSK137647 in the DSS model of colitis, we used a selective FFAR4 antagonist AH7614." (PMID 34444876, 2021). "This suggests that the FFAR4-PPARα axis may play a role in modulating M2 macrophage polarization, alleviating colitis." (PMID 41030455, 2025). "Consequently, our group discovered the anti-inflammatory properties of this FFAR4 agonist in colitis." (PMID 39432182, 2024). "Moreover, we concluded the study by investigating whether the co-administration of opioid antagonist naloxone and FFAR4 agonist GSK 137647 may influence parameters of colitis in mice." (PMID 34833919, 2021). "Administration of FFAR4 agonist GSK137647 attenuated both TNBS-induced and DSS-induced colitis in mice, as indicated by macroscopic parameters and myeloperoxidase activity." (PMID 34444876, 2021). "MOR agonist DAMGO administered twice daily at the dose of 0.02 mg/kg BW (i.p.)and FFAR4 antagonist AH 7614 administered twice daily at the dose of 1 mg/kg BW (i.p.)did not attenuate DSS-induced colitis alone or in co-administration, as indicated by inflammatory indicators." (PMID 34833919, 2021). "Our findings obtained in the DSS model of colitis confirmed that stimulation of FFAR4 significantly alleviated macroscopic parameters of colitis, with no apparent effect on the MPO activity, which suggests weak or perhaps lack of the effect on neutrophil infiltration." (PMID 34444876, 2021).
colorectal cancer (11 papers, 2017 to 2025). A primary or metastatic malignant neoplasm that affects the colon or rectum. "The literature has extensively examined the involvement of FFAR4 in colorectal cancer, while its association with lung cancer remains insufficiently elucidated." (PMID 38243188, 2024). "FFAR4 has been shown to promote tumorigenic behaviors including enhanced proliferation, migration, and angiogenesis in breast and colorectal cancers, and it would be of interest to know if FFAR4 also localizes to cilia in these cell types." (PMID 40301543, 2025). "We recently demonstrated that FFAR4 possesses tumor promoting properties in adipose tissues-adjacent malignancies like colorectal carcinoma." (PMID 30795784, 2019). "Although the role of FFAR4 in the development of CCA has not been clarified, in colorectal cancer, FFAR4 can promote angiogenesis and EMT by increasing the secretion of vascular endothelial growth factor (VEGF), IL-8, and prostaglandin E2 (PGE2)." (PMID 39984452, 2025).
Hepatic steatosis (9 papers, 2014 to 2024). Steatosis is a term used to denote lipid accumulation within hepatocytes. "FFAR4 deficiency blocked the protective effects of high endogenous n-3 PUFAs on intestinal barrier dysfunction and hepatic steatosis." (PMID 36771292, 2023). "In this study we showed for the first time in an in vivo model that the use of the synthetic FFAR4 stimulator (TUG-891) resulted in a significant reduction in fatty liver." (PMID 36705799, 2024). "Alterations in the abundances of these specific bacterial genera led to changes in the overall production of free fatty acids and their interaction manner with FFAR4, ultimately diminishing the protective mechanisms against hepatic steatosis." (PMID 39132138, 2024). "Because free fatty acid receptor 4 (FFA4, also known as GPR120) has been found as a receptor for n-3 PUFAs in an ethanol-induced liver steatosis model, we investigated whether n-3 PUFAs protect against liver steatosis via FFA4 using AH7614, an FFA4 antagonist, and Ffa4 knockout (KO) mice." (PMID 38791514, 2024).
atherosclerosis (8 papers, 2021 to 2025). A disease characterized by the build-up of fatty material and calcium deposition in the arterial wall resulting in partial or complete occlusion of the arterial lumen. "The major finding in this work is that inhibition of atherosclerosis by a selective FFAR4 agonist TUG-891 is associated with a significant shift in the polarization of macrophages in atherosclerotic plaques towards the M2 phenotype." (PMID 34575934, 2021). "Several in vitro studies describe how FFAR4 protects against the initial steps of atherosclerosis by regulating monocyte–endothelial cell interactions and endothelial cell–mediated inflammation." (PMID 40157537, 2025). "The activation of free fatty acid receptor 4 (FFAR4), also known as G protein-coupled receptor 120, reduces atherosclerosis and protects heart function." (PMID 38956679, 2024). "The stimulation of FFAR4 using selective synthetic agonists proved to be promising strategy of reduction of atherosclerosis and liver steatosis." (PMID 33923318, 2021). "In this paper, we summarize the evidence showing the mechanisms of the potential beneficial effects of FFAR4 stimulation in atherosclerosis." (PMID 33923318, 2021). "Taken together the available data promise FFAR4 as an important VSMC regulator in atherosclerosis; however, clearly more research is required to fully unravel their therapeutic potential." (PMID 33923318, 2021). "FFAR4-signaling was responsible for the maintenance of oxylipins in lipoproteins and may be a novel therapeutic strategy in the treatment of atherosclerosis." (PMID 37108233, 2023). "In vitro studies have pointed to many potential mechanisms by which FFAR4 pathway may intervene in cellular changes involved in atherosclerosis." (PMID 33923318, 2021). "Clearly, further research and dedicated experiments are required to fully explore and validate the potential of FFAR4 agonists in regulating the phenotype of macrophages toward an anti-inflammatory M2 activation state as a potential novel pharmacotherapy of atherosclerosis." (PMID 33923318, 2021). "It seems reasonable to assume, that attenuation of liver steatosis by stimulation of FFAR4 might represent an interesting strategy for the prevention of atherosclerosis." (PMID 33923318, 2021). "In view of the recognized role of macrophages in the development of atherosclerosis, inhibition of their activation by stimulation of FFAR4 may represent an interesting option as an anti-atherogenic strategy." (PMID 33923318, 2021). "Interestingly, there is a growing body of evidence that FFAs acting via FFARs may additionally show important anti-inflammatory effects, hence the stimulation of FFAR, including that FFAR4 might partly counterbalance unfavorable action of FAs in atherosclerosis." (PMID 33923318, 2021). "The information about FFAR4 role(s) in VSMC is scarce; however, two in vivo studies point to potentially important modulatory role of FFAR4 in VSMC pathology in atherosclerosis." (PMID 33923318, 2021). "In this study, our hypothesis was shown to be incorrect, suggesting that the cardioprotective effects of FFAR4 in atherosclerosis are independent of lipoprotein uptake and foam cell formation." (PMID 40157537, 2025). "Whether or not FFAR4 agonists prove to be compounds capable of limiting atherosclerosis by altering the phenotype of cells responsible for maintaining inflammation in the vessel wall remains an attractive hypothesis to be tested." (PMID 33923318, 2021).
metabolic syndrome (8 papers, 2016 to 2025). A cluster of metabolic risk factors for CARDIOVASCULAR DISEASES and TYPE 2 DIABETES MELLITUS. "Of note, previous reports have shown that abnormal cardiac function caused by an intracellular Ca2+ overload and reactive oxygen scavenger (ROS) accumulation are affected by dyslipidemia and that EPA rescues both via its receptor FFAR4-dependent or -independent pathways." (PMID 40085971, 2025). "In conclusion, our data provide evidence for alternative routes, not dependent on FFAR4, involved in mediating the beneficial effect of ω3-PUFAs, and emphasize the importance of ω3-PUFAs in relation to adequate immune regulation in curtailing the metabolic syndrome." (PMID 27999451, 2016).
prostate carcinoma (7 papers, 2017 to 2024). A carcinoma that arises from epithelial cells of the prostate gland. "FFAR1 activation promotes lung cancer and melanoma and prostate cancer, while FFAR4 activation inhibits these processes." (PMID 35785152, 2022). "Previous work in our group demonstrated that agonists for another GPCR, FFAR4, inhibit downstream responses to LPA in human prostate cancer cells as well as in breast and ovarian cancer cells." (PMID 38545253, 2024). "DHA significantly induced growth inhibition and apoptosis of human androgen-dependent prostate cancer cells via inactivating YAP by promoting phosphorylation and cytoplasmic translocation pathways (FFAR1/FFAR4-Gas-PKA-Hippo)." (PMID 36117589, 2022).